NRAP (nebulin related anchoring protein)
Description:
May be involved in anchoring the terminal actin filaments in the myofibril to the membrane and in transmitting tension from the myofibrils to the extracellular matrix.
Synonyms: N-RAP; CMD2N
Tractability: No criterion of Open Targets' tractability assessment is met for any kind of drug.
Gene: Protein-coding gene on chromosome 10 (113,588,714 to 113,664,121, reverse strand). Ensembl gene ENSG00000197893.
Subcellular location (Human Protein Atlas): Intermediate filaments; Cytosol; Vesicles
Gene Ontology:
Molecular function: protein binding; actin binding; actin filament binding; muscle alpha-actinin binding; vinculin binding
Biological process: cardiac muscle thin filament assembly
Cellular component: fascia adherens; muscle tendon junction; Z disc; cytoplasm; myofibril
Genetic constraint (gnomAD): Loss-of-function variants: 87 observed, 99.49 expected, observed/expected ratio (o/e) 0.87, 90% interval 0.73 to 1.04. The upper end of that interval is the gene's LOEUF score, 1.04, which puts it in group 4 of 6, group 1 being the genes least tolerant of losing a copy. Missense variants: 1,347 observed, 1,373.7 expected, observed/expected ratio (o/e) 0.98, 90% interval 0.94 to 1.03. Synonymous variants: 491 observed, 535.57 expected, observed/expected ratio (o/e) 0.92, 90% interval 0.85 to 0.99.
Gene-disease validity (ClinGen):
ClinGen rates the evidence that NRAP causes each of these diseases.
dilated cardiomyopathy (autosomal recessive): Strong. Cardiomyopathy which is characterized by dilation and contractile dysfunction of the left and right ventricles.
Homologues: Orthologues: chimpanzee NRAP (99% identical), macaque NRAP (98% identical), pig NRAP (91% identical), dog NRAP (90% identical), rabbit NRAP (90% identical), guinea pig NRAP (90% identical), rat Nrap (87% identical), mouse Nrap (86% identical), tropical clawed frog nrap (66% identical), zebrafish nrap (62% identical), Caenorhabditis elegans ltd-1 (4% identical), Drosophila melanogaster Hil (3% identical). Paralogues in human: NEB (38% identical), NEBL (12% identical), KY (4% identical), LASP1 (3% identical).
Diseases named in the same sentence as NRAP in open-access papers:
NRAP is named in the same sentence as 31 diseases in open-access papers, as found by Europe PMC text mining. Sharing a sentence is not in itself a finding about the gene and the disease. The quoted sentences say what the papers report.
dilated cardiomyopathy (7 papers, 2017 to 2025). "This study offers compelling genetic evidence that substantiates a shared ancestral origin for the identified NRAP homozygous LoF variant in two consanguineous Italian families affected by dilated cardiomyopathy." (PMID 41465143, 2025). "In 2017, an NRAP gene homozygous nonsense mutation (c.4504C > T) was first discovered in a patient with dilated cardiomyopathy (DCM)." (PMID 36815016, 2023). "The homozygous NRAP truncating variant (rs201084642), which is predicted to introduce premature stop codon into all NRAP isoforms, was revealed in the dilated cardiomyopathy patient using whole exome sequencing." (PMID 28611399, 2017). "Our findings suggest that the biallelic loss-of-function mutation in NRAP could constitute a relatively rare, low-penetrance genetic risk factor for dilated cardiomyopathy." (PMID 28611399, 2017). "In mice, NRAP is downregulated during dilated cardiomyopathy (DCM); human patients with DCM are homozygous for NRAP mutations." (PMID 33784744, 2021). "The expression of NRAP is upregulated in mice models of dilated cardiomyopathy (DCM), such as CSRP3/MLP knockout mice and tropomodulin overexpressing transgenic mice." (PMID 28611399, 2017). "Biallelic loss-of-function (LoF) variants in the nebulin-related anchoring protein (NRAP) gene have been linked to dilated cardiomyopathy (DCM) and left ventricular noncompaction cardiomyopathy, though only a few families have been described." (PMID 41465143, 2025).
cardiomyopathy (5 papers, 2016 to 2025). A disease of the heart muscle or myocardium proper. "NRAP-associated cardiomyopathies are predominantly attributable to homozygous LoF variants, with the majority of reported cases arising in the context of consanguinity." (PMID 41465143, 2025). "Consanguinity is frequently reported among NRAP-associated cardiomyopathy cases, and a founder effect has been described for the c.400_407del (p.Cys134Serfs*12) variant, which has been identified in multiple unrelated families, particularly within the Saudi Arabian population." (PMID 41465143, 2025). "They believed that NRAP truncation can cause childhood cardiomyopathies." (PMID 36815016, 2023). "In theory, the NRAP gene mutation may lead to musculoskeletal system disease and cardiomyopathy since NRAP is specifically expressed in heart and skeletal muscle." (PMID 36815016, 2023). "Few studies reported the association of the NRAP gene with cardiomyopathy." (PMID 36815016, 2023). "There are few clinical reports of NRAP gene mutation causing cardiomyopathy." (PMID 36815016, 2023). "Therefore, whether NRAP gene mutations directly lead to cardiomyopathy and its specific molecular mechanism need to be further studied." (PMID 36815016, 2023). "Biallelic loss-of-function (LoF) variants of NRAP have been associated with DCM or LVNC, strongly supporting its involvement in human cardiomyopathies." (PMID 41465143, 2025). "Taken together, these findings reinforce the critical role of NRAP in cardiomyopathy pathogenesis and highlight the importance of its inclusion in genetic testing strategies, particularly in populations with high rates of consanguinity or suspected founder variants." (PMID 41465143, 2025). "Numerous sarcomeric components/cytoskeletal proteins were identified as showing increased synthesis in our pSILAC experiments, several of which play important roles in cardiac function and/or in cardiomyopathies (e.g. desmin, vinculin, NRAP (nebulin-related anchoring protein) and Lmod)." (PMID 27512079, 2016).
nemaline myopathy (3 papers, 2020 to 2023). Nemaline myopathy (NM) encompasses a large spectrum of myopathies characterized by hypotonia, weakness and depressed or absent deep tendon reflexes, with pathologic evidence of nemaline bodies (rods) on muscle biopsy. "NRAP mutations manifest as DCM in young adults, NRAP overexpression results in right ventricle cardiomyopathy in mice and nemaline myopathy in zebrafish." (PMID 31952119, 2020). "We also studied the recently-discovered proteins associated with the development of nemaline myopathy, KLHL41 and NRAP." (PMID 31992366, 2020). "Downregulation of NRAP ameliorated the disease phenotype in zebrafish, suggesting that it could represent a therapeutic target in nemaline myopathy." (PMID 36703211, 2023). "NRAP is involved in myoblast fusion and myofibril assembly, and its accumulation has been detected in mouse and zebrafish models of KLHL41-related nemaline myopathy." (PMID 36703211, 2023).
Hernia (1 paper, 2023). "Yet the presence of a group of mutated genes linked to myopathies (ITGA7, NRAP, POLM, SCN5A, XIRP2) and muscular dystrophy (ITGA7) raises a question about the involvement of these muscular pathologies in hernia genesis and unsuccessful hernia repairs associated with the current case." (PMID 38021525, 2023).
migraine (1 paper, 2021). "SNP rs181024055 in NRAP was associated with later AoM in all migraine cohort analysis." (PMID 34380431, 2021). "Furthermore, rs181024055 in NRAP is associated with late AoM in the migraine without aura group." (PMID 34380431, 2021). "The involvement of NRAP in migraine pathogenesis has not been described." (PMID 34380431, 2021).
rheumatic diseases (1 paper, 2022). "Anti-NRAP autoantibodies were highly associated with PsA compared to PsO, RA CCP+ or CCP-, HC and the others rheumatic diseases included." (PMID 36532039, 2022). "Anti-NRAP autoantibodies were recognized by 83% of PsA sera, versus 7% of rheumatoid arthritis (RA) anti-CCP positive, 4% of RA anti-CCP negative, 3.3% of PsO, and none of other rheumatic diseases included in this study." (PMID 36532039, 2022).
Right ventricular cardiomyopathy (1 paper, 2020). Right ventricular dysfunction (global or regional) with functional and morphological right ventricular abnormalities, with or without left ventricular disease. "Overexpression of NRAP in the murine heart results in right ventricular cardiomyopathy, with little effect on the left ventricle and intercalated disc structure, questioning the role of N-RAP in the disease." (PMID 32661904, 2020).
myopathies (3 papers, 2017 to 2023). "We have previously shown that reduced ubiquitylation and upregulated protein level of an early sarcomeric protein, NRAP, in KLHL41 deficient skeletal muscle contributes to myopathy by abnormal sequestration of the late sarcomeric proteins and preventing their localization to mature sarcomeres." (PMID 37432316, 2023). "Notably, mutations in NEB, NRAP, and FLNC have been associated with NM and other myopathies." (PMID 28826497, 2017).
autosomal recessive disease (1 paper, 2023). Autosomal recessive form of disease. "With our study, we provided Moderate or Strong level of evidence for GDR for 11 genes that were not listed in OMIM as having phenotype entity: FBRSL1, AGR2, ACBD6, C1orf127, PAN2, VPS50, KCTD3, NOTCH3 (for autosomal recessive disease), FAT1, NRAP, and SCLT1." (PMID 39669245, 2023).
cardiac disease (1 paper, 2023). "The results indicated that NRAP gene mutation can be involved in BPs such as myocardial contraction and cell adhesion, causing cardiac disease." (PMID 36815016, 2023). "Although there was evidence that NRAP plays an important role in myocardial architecture and sarcomere function, no variant in this gene has been conclusively linked to heart disease to date." (PMID 36815016, 2023).
NRAP also shares sentences with these, for which no sentence is quoted: hypertrophic cardiomyopathy (2 papers); myofibrillar myopathy (2); ankylosing spondylitis (1); arrhythmogenic right ventricular cardiomyopathy (1); atrial fibrillation (1); cardiovascular diseases (1); connective tissue disorder (1); Desminopathy (1); familial cardiomyopathies (1); filaminopathy (1); left ventricular non-compaction cardiomyopathy (1); Left ventricular noncompaction cardiomyopathy (1); male infertility (1); muscular dystrophy (1); musculoskeletal system disease (1); myotilinopathy (1); osteosarcoma (1); psoriasis (1); rheumatoid arthritis (1); Sjogren syndrome (1); systemic sclerosis (1).